SLC7A11 (solute carrier family 7 member 11)
Diseases named in the same sentence as SLC7A11 in open-access papers (continued):
Sharing a sentence is not in itself a finding about the gene and the disease.
liver fibrosis (continued). "Specifically, CBD appears to exert its anti-liver fibrosis and antioxidative effects by activating CB2R, inhibiting the expression of α-SMA and ACSL4 proteins, and enhancing the expression of SLC7A11 protein, thereby alleviating liver damage." (PMID 40160456, 2025). "Through enhancing the ubiquitination of the Solute Carrier family-7 member-11 (SLC7A11), TRIM26 triggered ferroptosis in Hepatic Stellate Cells (HSC), ultimately reducing liver fibrosis." (PMID 38956921, 2024). "Together, these results indicated that BMSC-derived exosomal miR-26a reduced the level of SLC7A11 and relieved CCL4-induced liver fibrosis in mice." (PMID 38756248, 2024). "In a CCL4-induced mouse model of hepatic fibrosis, HSCs in the GSH depletion state, with low SLC7A11/xCT expression and E3 ubiquitin ligase TMCP26 overexpression, triggered ferroptosis, while fibrosis was effectively alleviated." (PMID 39358326, 2024). "In vivo, miR-26a mimic-Exo decreased the level of SLC7A11 and attenuated CCL4-induced liver fibrosis." (PMID 38756248, 2024). "The process is driven by TRIM26-mediated ubiquitination and degradation of SLC7A11, making TRIM26 a promising therapeutic agent against liver fibrosis." (PMID 37867509, 2023). "Tripartite motif-containing protein 26 (TRIM26) induces HSC ferroptosis through the regulation of solute carrier family-7 member-11 (SLC7A11) ubiquitination, thereby ameliorating liver fibrosis." (PMID 37007035, 2023). "Although some articles do not specifically describe SLC7A11-related ferroptosis, they document how promoting ferroptosis in HSCs can effectively improve liver fibrosis." (PMID 40249927, 2025). "In summary, the inconsistent effects of SLC7A11 on different liver cells suggest that it does not exert a singular effect on liver fibrosis." (PMID 40249927, 2025). "Antituberculosis drugs may induce ferroptosis in hepatocytes through the HIF-1α/SLC7A11/GPX pathway, leading to liver fibrosis." (PMID 40249927, 2025). "In nonalcoholic steatohepatitis (NASH) models, the downregulation or absence of AGER1 decreased SLC7A11 expression, thereby inducing hepatocyte injury and exacerbating liver fibrosis." (PMID 40249927, 2025). "Specifically, SLC7A11 upregulation in hepatocytes initially affects liver cells and influences HSCs via the extracellular pathway, thereby attenuating HSC activation and protecting against liver fibrosis." (PMID 40249927, 2025). "Knockdown of FRMD6-AS1 significantly increased iron ion, ROS, and MDA levels in activated HSCs while reducing GSH levels and the expression of SLC7A11 and GPX4 proteins, inducing ferroptosis in HSCs, thereby restoring liver tissue structure and reversing liver fibrosis." (PMID 39717848, 2024). "Interestingly, Dan attenuated LPS‐induced liver fibrosis in those cells by upregulating collagen I, CTGF, Gpx4, and SLC7A11 and by increasing lipid reactive oxygen species accumulation." (PMID 36655094, 2023). "These extracts administered to mice also inhibited ferroptosis in the liver by regulating the expression of Acyl-CoA synthetase long chain family member 4 (ACSL4), solute carrier family 7 member 11 (SLC7A11) and glutathione peroxidase 4 (GPX4), thus reducing the occurrence of liver fibrosis." (PMID 37032323, 2023). "Some researchers found HIF-1α/SLC7A11 pathway affected liver fibrosis through the mechanism of ferroptosis, but they did not explore the regulatory mechanism." (PMID 36439690, 2022).
non-small cell lung carcinoma (31 papers, 2018 to 2025). A group of at least three distinct histological types of lung cancer, including non-small cell squamous cell carcinoma, adenocarcinoma, and large cell carcinoma. "In contrast, EGFR mutations in non-small cell lung cancer cells render them more susceptible to SLC7A11 inhibition or cysteine deprivation because intracellular cysteine promoted survival EGFR-mutant cells independent of GSH-relater redox balance." (PMID 36864513, 2023). "Likewise, SLC7A11 was found to be highly expressed in the cytoplasmic membrane in non-small-cell lung carcinoma (NSCLC) and is associated with poorer prognosis." (PMID 35280777, 2022). "Recent studies have reported that factors such as SLC7A11, NRF2, and xCT are involved in the process of ferroptosis in non-small cell lung cancer." (PMID 39594843, 2024). "For example, circ0082374 and SLC7A11 reciprocally control their expression levels in non-small cell lung cancer cells." (PMID 38994627, 2024). "For instance, in non-small cell lung cancer, Erastin and Sorafenib, either alone or in combination, induce ferroptosis by inhibiting the Nrf2/SLC7A11 (also known as xCT) pathway, thereby overcoming DDP resistance." (PMID 38239395, 2023). "In conclusion, we demonstrated that AhR inhibits iron-dependent cell death (i.e., ferroptosis) in human non-small cell lung cancer cells by binding to the promoter region of SLC7A11, a transcription factor." (PMID 37056388, 2023). "XAV939 induces ferroptosis and inhibits non-small cell lung cancer (NSCLC) by downregulating SLC7A11 through long non-coding RNA (lncRNA)." (PMID 38273826, 2023). "SLC7A11 also promotes the growth and development of non-small cell lung cancer and corresponds to shorter 5-year survival of patients." (PMID 37940859, 2023). "The progression of non-small cell lung cancer was promoted by xCT- (SLC7A11-) mediated metabolic reprogramming." (PMID 34531924, 2021). "As indicated by our findings, many miRNAs could not only regulate the occurrence and development of osteoporosis, but also participate in the process of ferroptosis, as indicated by the evidence that miR-27a-3p targeted SLC7A11 directly in non-small cell carcinoma cells to regulate ferroptosis." (PMID 38509680, 2024). "For example, in non-small cell lung cancer (NSCLC), METTL3 acts as a catalyst for ferroptosis by targeting GPX4 and SLC7A11." (PMID 40271153, 2025). "On the other hand, NEAT1 inhibits erastin-induced ferroptosis by not only increasing GPX4 and SLC7A11-mediated antioxidative pathways but also decreasing ACSL4-mediated lipid peroxidation, which may confer the resistance to erastin in non-small cell lung cancer (NSCLC) cells." (PMID 35625948, 2022).
Sepsis (30 papers, 2007 to 2025). Sepsis is defined as life-threatening organ dysfunction caused by a dysregulated host response to infection. "In fact, numerous studies have consistently highlighted the significant role of ferroptosis in the development of sepsis-induced heart injury, and Ptgs2, Hmox1, and Slc7a11 are well-recognized ferroptosis-associated targets by academia." (PMID 37424906, 2023). "METTL3 promotes Slc7a11 mRNA degradation through m6A-dependent mechanisms, intensifying sepsis-induced cardiomyocyte ferroptosis—an iron-dependent, lipid per oxidation-mediated cell death strongly implicated in sepsis pathogenesis." (PMID 41341492, 2025). "Therefore, our study first demonstrated two novel ferroptosis-associated targets in sepsis-induced cardiac injury: Hmox1 and Slc7a11 through bioinformatic selection and laboratory measurement." (PMID 37424906, 2023). "This study reports Hmox1 and Slc7a11 as ferroptosis-associated targets in sepsis-induced cardiac injury, and both of them may become key therapeutic and diagnostic targets for this complication in the future." (PMID 37424906, 2023). "In addition to Ptgs2 as a recognized biomarker in sepsis-induced cardiac injury, Hmox1 and Slc7a11 were reported as ferroptosis-associated targets in sepsis cardiac dysfunction." (PMID 37424906, 2023). "First, while we established the protective role of the Piezo1/BHLHE40/SLC7A11 axis in LPS-induced sepsis, its function in chronic vascular diseases such as atherosclerosis requires validation in respective animal models and clinical specimens." (PMID 41372156, 2025). "N6-methyladenosine writer METTL3 can also accelerate the sepsis-induced myocardial injury by m6A modification of SLC7A11 via YTHDF2 pathway." (PMID 40356926, 2025). "Inhibiting SLC7A11 during sepsis leads to SXc− inactivation, the prevention of cystine translocation into cells, and reduced glutathione synthesis from glutamate and cystine." (PMID 38601213, 2024). "Transcription factors such as forkhead box O3 and nuclear factor kappa B required for muscle atrophy are activated during sepsis, and these transcription factors inhibit SLC7A11 expression which causes the inhibition of the SXc−-GSH-GPX4 signaling pathway." (PMID 38601213, 2024). "The fold change of Ptgs2, Hmox1, and Slc7a11 in sepsis-induced heart injury increased in 24 h and decreased in 48 and 72 h, which exhibited the same time trend as found previously." (PMID 37424906, 2023). "The findings from our study revealed elevated levels of Slc7a11 in the sepsis group, indicating that the more complicated mechanisms between Slc7a11 and ferroptosis in various diseases should be investigated in the future." (PMID 37424906, 2023). "Meanwhile, two novel ferroptosis-related targets were also selected in sepsis-induced cardiac injury: Hmox1 and Slc7a11." (PMID 37424906, 2023). "The results showed that Hmox1 and Slc7a11 expressed highly in the sepsis group than in the control group." (PMID 37424906, 2023). "While Ptgs2 has been previously reported to be involved in the regulation of septic cardiomyopathy, this study is the first to demonstrate that downregulation of Hmox1 and Slc7a11 can alleviate ferroptosis in sepsis-induced cardiac injury." (PMID 37424906, 2023).
Sepsis (continued). "For the sake of comprehensiveness, GSE215955 and GSE53007 were used to validate the expression patterns of Hmox1 and Slc7a11, revealing that Hmox1 and Slc7a11 also had high expression in the sepsis group." (PMID 37424906, 2023). "In order to further investigate the role of Ptgs2, Hmox1, and Slc7a11 in sepsis-induced cardiac injury, we first investigated their expression levels in each group." (PMID 37424906, 2023). "The findings indicate that BAT-derived Nrg4 suppresses ferroptosis and attenuates sepsis-induced liver injury by promoting the expression of SLC7A11, GSH, and GPX4, suggesting potential therapeutic application of BAT activation and its secreted Nrg4 in treating septic liver injury." (PMID 39956880, 2025). "Additionally, miR-31-5p alleviates sepsis-induced cardiomyopathy by inhibiting the deubiquitination of SLC7A11 via targeting BAP1, thereby also counteracting ferroptosis." (PMID 40041174, 2025). "Furthermore, the increase in ROS causes an increase in iron content and alterations in the proteins GPX4, ACSL4, and SLC7A11, recognizing the role of ferroptosis in sepsis-related brain degeneration." (PMID 39768830, 2024). "In addition, the time-course expressions of Ptgs2, Hmox1, and Slc7a11 in the model of sepsis-induced cardiac injury induced by the injection of LPS were also analyzed." (PMID 37424906, 2023). "Likewise, YTHDF2 recognizes METTL3-mediated m6A modification of SLC7A11 mRNA and promotes the degradation of SLC7A11 mRNA, ultimately leading to ferroptosis in sepsis-induced myocardial injury." (PMID 38112620, 2023). "Consistent findings were observed in LPS-induced sepsis, where CL316243-treated mice showed reduced liver MDA levels and increased GSH, SLC7A11, and GPX4 expression." (PMID 39956880, 2025). "WB revealed a significant upregulation of SLC7A11 and GPX4 expression, suggesting that rNrg4 mitigated the ferroptosis observed in sepsis-induced liver injury." (PMID 39956880, 2025). "In sepsis, TNF-α and IL-1β downregulate its subunit SLC7A11, reducing GSH levels by 40%–60% in lung tissues." (PMID 41383584, 2025). "For example, the NRF2 pathway inhibits ferroptosis and reduces sepsis-induced lung tissue damage by upregulating antioxidant proteins such as GPX4 and SLC7A11." (PMID 41250137, 2025). "Similar results were seen in LPS-induced sepsis, where liver MDA levels were elevated, and GSH, SLC7A11, and GPX4 expression was diminished in BAT-excised mice." (PMID 39956880, 2025). "It plays significant roles in sepsis pathogenesis, with key molecular markers including PTGS2/COX2, SLC7A11 and GPX4." (PMID 40822455, 2025). "The results demonstrated a marked decrease in the expression of GPX4 and SLC7A11, while PTGS2 expression was significantly increased in liver tissues of the septic mice, suggesting that sepsis induces ferroptosis in liver tissues." (PMID 39512683, 2024). "The m6A modified SLC7A11 mRNA was recognized by YTHDF2, which promoted the decay of SLC7A11 mRNA, consequently up-regulating ferroptosis in sepsis-induced myocardial injury." (PMID 39234245, 2024). "The six intersection disulfidptosis‐related genes including LRPPRC, SLC7A11, GLUT, MYH9, NUBPL and GYS1 exhibited higher predictive ability for sepsis with an accuracy of 99.7%." (PMID 39400961, 2024). "Western blot analysis of ferroptosis-related proteins revealed that sepsis altered the expression of 4-HNE, FTH1, GPX4, ACSL4, PTGS2, and SLC7A11, which was reversed by ghrelin and Fer-1, indicating their role in inhibiting ferroptosis." (PMID 39857660, 2024).
Sepsis (continued). "In the mouse model of sepsis, LPS treatment significantly induced the expression of PTGS2 and SLC7A11, and upregulated the levels of iron and MDA in lung tissues, while Pyk2 inhibitor TAE226 decreased these positive markers of ferroptosis." (PMID 37886006, 2023). "Moreover, Ferrostatin-1, the inhibitor of ferroptosis, was found to rescue the downregulation of ferroptosis markers including cysteine/glutamate transporter (SLC7A11) and GPX4 in sepsis induced ALI/ARDS." (PMID 41383584, 2025). "One study has shown that in lipopolysaccharide (LPS)-induced sepsis models, the levels of iron and ROS in alveolar epithelial cells were increased significantly, while GSH levels were decreased, and the expression of GPX4 and SLC7A11 was significantly downregulated." (PMID 41250137, 2025).
triple-negative breast carcinoma (27 papers, 2015 to 2026). An invasive breast carcinoma which is negative for expression of estrogen receptor (ER), progesterone receptor (PR), and human epidermal growth factor receptor 2 (HER2). "Meanwhile, MUCIN 1 (MUC1) could bind to the CD44 variant to enhance the stability of SLC7A11, thereby inhibiting erastin-induced ferroptosis in triple-negative breast cancer cells." (PMID 35795552, 2022). "Overexpression of xCT/SLC7A11 has been reported in triple-negative breast cancer (TNBC), where its activity fuels cysteine supply for GSH production; conversely, xCT inhibition reduces proliferation, partly through GSH depletion." (PMID 41333220, 2025). "We found that when IRE1α was depleted in MDA-MB-231 triple-negative breast cancer cells, these cells became significantly more resistant to ferroptotic cell death induced by either erastin, an inhibitor of the cystine-glutamate antiporter SLC7A11, or cystine depletion." (PMID 38750057, 2024). "We previously found that about 1⁄2 of triple negative breast cancer (TNBC) clinical specimens and TNBC-derived cell lines overexpress xCT/SLC7A11." (PMID 30190786, 2018). "The amino acid transporters SLC38A5 and SLC7A11 are upregulated in triple-negative breast cancer (TNBC)." (PMID 38539825, 2024).
diabetes (24 papers, 2020 to 2025). "MYC and SLC7A11 were particularly notable, showing upregulated expression in DR samples and involvement in apoptosis and diabetes-related pathways." (PMID 39634176, 2024). "Metformin, already used in the treatment of diabetes, was recently described as promoting ferroptosis in different ways, including by the inhibition of SLC7A11." (PMID 36899869, 2023). "The SLC7A11 immunoreactivity was marked and extended across the entire neural retina to the IS in the control mice, whereas the expression of SLC7A11, especially in the IS, was simultaneously downregulated in the retinas at 1 and 3 months post-diabetes." (PMID 38069270, 2023). "In a recent paper published in Nature, Maschalidi and colleagues described the inhibition of SLC7A11 function in dendritic cells (DCs) as a crucial regulator for acceleration of wound healing in diabetes." (PMID 36104337, 2022). "Diabetes-prone mice suffer from reduced efferocytosis and low GDF15 levels, both associated with high SLC7A11 expression, showing a significantly slower healing process." (PMID 36104337, 2022). "It has been confirmed that patients with T2DM and its complications are devoid of GSH, with evidence also establishing that the role of SLC7A11-mediated ferroptosis in diabetes and its complications." (PMID 35992146, 2022). "Regarding pancreatic β cells dysfunction in diabetes, only one study has suggested that upregulation of xCT (SLC7A11) expression was observed in the islet of T2D mice." (PMID 35992146, 2022). "We identified significant associations between cg10601624, cg06690548 (SLC7A11), cg19693031 (TXNIP), and cg00574958 (CPT1A) and TOD in the kidney even further after adjustment for BMI, smoking status, and diabetes." (PMID 32917208, 2020). "Moreover, resveratrol also upregulated the expression of GPX4 and SLC7A11 in osteocytes during diabetic periodontitis conditions in vitro in the same fashion that ferrostatin-1 did." (PMID 37432277, 2023). "Although this review delves into the critical role of SLC7A11 in diabetic wound healing, it must be acknowledged that diabetic wound healing is a multifactorial-driven complex process involving various aspects, such as angiogenesis, microbial infection, and diabetes-induced systemic complications." (PMID 39290692, 2024). "The expression of SLC7A11, GPX4, FSP1, FTH1, and FPN1 were suppressed, while TFR1 was elevated in the kidney injury induced by diabetes." (PMID 39630101, 2025). "This includes investigating myocardial ferroptosis and assessing NAC treatment in animals with longer durations of diabetes, and mining the factors contributing to the reduction of GPX4 or Slc7a11 in the early stages of diabetes." (PMID 38647950, 2024). "Thirdly, the specific mechanism by which ferroptosis regulates visual pathway damage in diabetes, such as GPX4/xCT/SLC7A11 and NAD(P)H/FSP1/CoQ10 systems, needs to be further explored and verified in vitro." (PMID 39080199, 2024). "The inverse association between DNA methylation and UACR was stronger in those with diabetes (cg14476101 in PHGDH, cg19693031 in TXNIP, and cg06690548 in SLC7A11) or those who were obese (cg06690548 in SLC7A11)." (PMID 32917208, 2020). "Our current findings show that under natural conditions of diabetes, especially before D5w, D1w as well as D2w exhibited no or little change in ferroptosis-related proteins such as Gpx4 and Slc7a11, while at D5w this change became pronounced." (PMID 38647950, 2024). "However, compared to the earlier changes in Gpx4, significant downregulation of Slc7a11 did not occur until at week-5 of diabetes (p < 0.05)." (PMID 38647950, 2024).